NOTCH1 (notch receptor 1)
Diseases named in the same sentence as NOTCH1 in open-access papers (continued):
Sharing a sentence is not in itself a finding about the gene and the disease.
lymphoma (continued). "Activated mutations in NOTCH1 are drivers of T-cell type acute lymphoblastic leukemia/lymphoma." (PMID 36243685, 2022). "Due to the constitutive activation of deletion mutations, the abnormal increase in Notch1 transcription in fusion T-lymphoma mice may be due to the use of an alternative Notch1 promoter." (PMID 36408177, 2022). "We also detected frequent activating Notch1 mutations in lymphomas from PPM1D-transgenic mice." (PMID 34771656, 2021). "In total, five lymphoma samples had distinct Notch1 mutations." (PMID 31959748, 2020). "Recently, a variant in the extracellular domain of Notch 1 that provides a growth advantage to cells and confirms the suitability of the Notch pathway as a second-line druggable target was found in a severe form of lymphoma—the anaplastic large cell lymphoma." (PMID 33374160, 2020). "Importantly, a conditional K-RasG12D (where Glycine in codon 12 is mutated to Aspartic acid in K-Ras) knock-in mouse model develops T-cell leukemia/lymphoma and Ras activating mutations cooperate with NOTCH1 mutations to drive T-ALL development." (PMID 28872614, 2017). "Indeed, Notch1 is a well-characterized oncoprotein in T-ALL and lymphomas where activating Notch1 mutations are responsible for approximately 60% of T-ALL cases." (PMID 29387053, 2017). "Interestingly, the Tcf1−/− thymic lymphomas easily gain additional mutations in the Notch1 gene (in contrast to the β-catenin-dependent lymphomas), which leads to further development of these lymphomas." (PMID 23185135, 2012). "Perturbation of NOTCH1 signaling has been shown in different solid tumors such as lung, breast, liver, gastric and prostate carcinomas and hematologic malignancies such as lymphomas, T-ALLs and CLLs, where it is associated with EMT and cancer stem cells self-renewal and preservation." (PMID 27980227, 2017). "In mouse models, NOTCH1 inhibition decreased lymphoma cell activity and proliferation, as indicated by reduced fluorescence intensity and distribution." (PMID 39951437, 2025). "Results showed decreased lymphoma cell activity and proliferation in the NOTCH1 knockdown group compared to the control group." (PMID 39951437, 2025). "NOTCH1 mutations have been found also in ~1/3 cases of the clinically aggressive blastoid variant of MCL, further suggesting a link between NOTCH1 and lymphomas with high-grade features." (PMID 38638855, 2024). "The results showed that the expression level of Notch-1 in KO + lymphoma cell + IXA4 group remained very low compared with WT + lymphoma cell + IXA4 group (P < 0.01), but was similar to that in KO group." (PMID 38261741, 2024). "The expressions of IL-4 and IL-6 in KO + lymphoma cell group were significantly inhibited compared with WT + lymphoma cell group, demonstrating that Notch-1 is a key upstream molecule regulating the expressions of IL-4 and IL-6." (PMID 38261741, 2024). "The effect of myeloid-specific knockout of Notch-1 on lymphoma progression was observed by mouse tumor transplantation and imaging." (PMID 38261741, 2024). "The results demonstrated that lymphoma cells can activate the Notch-1 downstream STAT3/STAT6 signaling pathway." (PMID 38261741, 2024).
lymphoma (continued). "The expression levels of p-AKT, CD9, CD63 and PD-L1 in KO + lymphoma group were significantly lower than those in WT + lymphoma group, demonstrating that Notch-1 is a key upstream molecule for the activation of AKT pathway in macrophages." (PMID 38261741, 2024). "The lymphomas with NOTCH1 positivity also showed expression of TCRβ (12/12) on their surface with no expression of TCRγ (0/12)." (PMID 37160922, 2023). "As previously reported for mantle cell lymphoma, NOTCH1 and NOTCH2 mutations occurred mutually exclusively suggesting a similar oncogenic advantage for affected lymphoma cells." (PMID 36604606, 2023). "We demonstrate that there is decreased NUMB and increased MDM2 expression in NOTCH1 overexpressing lymphomas." (PMID 37160922, 2023). "Given that many of the T-cell malignancies in the Vav1-P53CKO mice resemble those in human T-ALL, we stained the lymphoma cells for NOTCH1." (PMID 37160922, 2023). "In a mouse model of the FOP2-FGFR1 fusion, the fusion protein combined with Notch1 promoted stem cells to differentiate into T cells and trigger lymphoma." (PMID 36408177, 2022). "Due to their differential role in B and T-cell physiology, the Notch 2 member seems to be the most involved in lymphomagenesis even if a few Notch 1 signaling alterations were described in low as well as high grade lymphomas." (PMID 33374160, 2020). "In two gamma radiation-induced lymphomas we found focal amplification of Notch1, one of which also carried a point mutation, demonstrating the multiplicity of mechanisms leading to activation of Notch1 in radiation-induced lymphomas." (PMID 31959748, 2020). "More recently, next generation sequence analysis of five cases of MALT lymphomas revealed the presence of Notch 1 alteration in three patients, but further studies are needed to explore the contributions in this lymphoma subtype." (PMID 33374160, 2020). "We also observed recurrent gene-level events in Notch1, a gene known to play an important role in radiation-induced lymphoma development." (PMID 31959748, 2020). "In fact in these lymphomas, NOTCH1 was found to directly transcriptionally regulate LEF1 expression." (PMID 28872614, 2017). "Real-time RT-PCR confirmed that Notch1, Notch3, Hes1 and Myc mRNA levels were upregulated in Lck-Dlx5 lymphomas, when compared with those of WT thymic T-cells and Lck-MyrAkt2 lymphomas." (PMID 28122332, 2017). "For example, several genes previously identified in other types of lymphomas, such as NOTCH1, POU2F2, CXCR4, and IGF1R, were affected by mutations." (PMID 28152507, 2017). "Immunohistochemistry also confirmed that Notch1, Notch3, Hes1, Myc and phospho (active)-Akt are upregulated in primary and metastatic lymphomas from Lck-Dlx5 mice." (PMID 28122332, 2017). "Activation of NOTCH1 by intragenic deletion of the Notch 1 exon 1 is common in lymphomas and irradiated thymi." (PMID 27542204, 2016). "We demonstrated that mice homozygous for dnTGFβRII spontaneously developed lymphoma-like T cell infiltration involving both the spleen and liver with a significantly elevated pro-oncogene expression of Notch 1 and c-Myc." (PMID 23145171, 2012). "The active intracellular form (ICN) of the transcription factor Notch1 is well documented to confer GC resistance upon lymphoma cells and 2B4 T cells." (PMID 22319533, 2012). "Third, Rag-mediated internal deletions in the Notch1 locus were detected in DKO lymphomas, suggesting continuous Rag gene activity during the evolution of the transformed clones." (PMID 19907659, 2009). "The synergistic effect of NOTCH1 and KDM6B mutations therefore may accelerate lymphoma progression by activating oncogenic pathways via chromatin remodeling." (PMID 38566223, 2024).
lymphoma (continued). "In addition, we found that the majority of the lymphomas showed a dramatic change in the RNA isoform of Ikaros, which is known to be a repressor of Notch1 target genes." (PMID 37160922, 2023). "Interestingly, we found that NOTCH1 on the cell surface was increased in lymphomas compared to normal thymi." (PMID 37160922, 2023). "The lymphomas in our mice represent a range of differentiation stages but retain NOTCH1 expression." (PMID 37160922, 2023). "Integrated ChIP-seq and mRNA microarray analyses identified Notch1/3 and Irs2 as direct transcriptional targets of Dlx5, a gene signature unique to lymphomas from Lck-Dlx5 mice as compared to T-cell lymphomas from Lck-MyrAkt2 mice, which were previously reported by our group." (PMID 28122332, 2017). "Further upregulation of Notch1/3 protein levels was observed in Lck-Dlx5 lymphoma cells." (PMID 28122332, 2017). "In a previous report, NOTCH1 mutations have been identified as the most common lesions occurring in Richter syndrome (RS), thus closing the loop to the frequent presence of tri12 in this rare transformation from CLL into an aggressive lymphoma." (PMID 25895128, 2015). "In addition, GATA3 appears to promote carcinogenesis in a lymphoma model induced by the increased expression of c-Myc, which in turn induces Notch1 and GATA3 as putative transcriptional targets that cooperate with Myc to establish a malignant phenotype." (PMID 24205108, 2013). "Therefore we examined the mRNA levels of the lymphoma-related proto-oncogenes involved in the Notch-1 signal pathway, including Notch-1, DLL1/4, Hes-1, PTEN and c-Myc in the liver tissues of individual animals." (PMID 23145171, 2012). "Further analysis of this panel of lymphomas showed that the expression levels of Hes1 and Deltex1, two target genes of Notch1 signaling, were enhanced in all tumor samples compared to the control samples, again demonstrating that both the Wnt and Notch pathway are involved in full lymphomagenesis." (PMID 23185135, 2012). "However, Hes1 transgenic mice develop lymphomas with a much longer latency and with a lower frequency compared to Notch1 or Notch3 expressing animals." (PMID 19688092, 2009). "Myeloid-specific knockout of Notch-1 could inhibit the progression of lymphoma." (PMID 38261741, 2024). "Immunoblotting uncovered upregulation of Notch1/Notch3 in tumors from Lck-Dlx5 and Lck-Dlx5;Lck-MyrAkt2 mice, upregulation of Myc in tumors from Lck-Dlx5, Lck-MyrAkt2, and Lck-Dlx5;Lck-MyrAkt2 mice, and upregulation of β-catenin uniquely in lymphomas from Lck-Dlx5;Lck-MyrAkt2 mice." (PMID 32985581, 2020). "Additionally, genetic alterations in Notch 1 signaling, with the subsequent overexpression and activation of the Myc pathway, were present in 30% of cases relating to Richter Syndrome, which is an aggressive lymphoma evolving from CLL." (PMID 33374160, 2020). "Once Notch1 expression is established, it may serve as an accelerator of the Lef1-mediated deregulated Wnt signaling, ensuring increased survival and expansion of the lymphoma cells." (PMID 23185135, 2012). "Lymphoma cells enhanced the expression of p-PERK, p-IRE1α, ATF6, IL-6, IL-4, p-AKT, CD9, CD63 and PD-L1 in bone marrow-derived macrophages by mediating the Notch-1 signaling pathway." (PMID 38261741, 2024).
lymphoma (continued). "In addition, these cells had higher levels of the transcription factor Hes1 suggesting that NOTCH signalling might play a role in malignant transformation in GATA3-overexpressing cells, presumably via c-MYC, which is a direct target of NOTCH1 in T lymphoblastic leukaemia/lymphoma." (PMID 35681778, 2022). "In two lymphomas, we found frameshift indels in the PEST domain, resulting in activation of Notch signalling, as well as multiple nonsynonymous SNVs in Notch1." (PMID 31959748, 2020). "Subset #4 is the largest subset of mutated IGHV CLL and is characterized by lower CD38 expression and the absence of NOTCH1- and SF3B1 mutations, while subset #8 has a higher risk for transformation into an aggressive lymphoma (Richter transformation)." (PMID 38835970, 2024). "NOTCH1, which directly targets MYC, is considered a common noncanonical Notch signal mediator and is closely associated with lymphoma tumorigenesis and SACC progression." (PMID 36879115, 2023). "The reason why mRNA levels of Notch1 and Notch3 were 2–4 fold greater in lymphoma cells than in normal T cells from Lck-Dlx5 mice was not due to gene amplification, as array-CGH analysis revealed no change of Notch1/3 gene copy number." (PMID 28122332, 2017). "A second RIM/DS screen comparing lymphomas of wild-type and parental transgenics showed that CD2-MYC tumours are virtually dependent on activation of Runx family genes in strong preference to other potent Myc collaborating genes (Gfi1, Notch1)." (PMID 24586197, 2014). "Interestingly, in the original paper describing a role for Notch1 in conferring GC resistance, overexpressing ICN in AKR1010 lymphoma cells led to the induction of Bcl-2." (PMID 22319533, 2012). "On the other hand, deletions at the Notch1 locus were found in the respective lymphomas but not in premalignant cells." (PMID 19907659, 2009). "One possible reason for this is that a Notch1/3 enhancer-specific coactivator generally may be lacking in Lck-MyrAkt2 lymphoma cell lines expressing Dlx5." (PMID 28122332, 2017). "The results suggested that the Notch-1 expression in the bone marrow-derived macrophages of Notch-1 conditional knockout mice is consistently suppressed and remains unchanged regardless of whether they are co-cultured with lymphoma cells and whether IXA4 is used." (PMID 38261741, 2024).
chronic lymphocytic leukemia (70 papers, 2012 to 2026). "Mutations in NOTCH1, which occur in ~10% of Chronic Lymphocytic Leukemia (CLL) patients at diagnosis, are typically associated with unmutated (UM) B-cell receptor (BCR) subsets and define patients with earlier treatment need." (PMID 41872504, 2026). "FBXW7 mutations reduce the binding of NOTCH1, leading to cleaved NOTCH1 accumulation and target gene activation in chronic lymphocytic leukemia." (PMID 38485719, 2024). "Overexpression of Notch1 intracellular domain (NICD) is also observed in the primary chronic lymphocytic leukemia (CLL) cells activated by FBXW7 mutation." (PMID 36998461, 2023). "Investigation of NOTCH1 mutations in chronic lymphocytic leukemia has aroused in advance the clinical significance of NOTCH signaling as a therapeutic target in human cancer." (PMID 38053150, 2023). "Mutations of the NOTCH1 gene are a validated prognostic marker in chronic lymphocytic leukemia and a potential predictive marker for anti-CD20-based therapies." (PMID 35740661, 2022). "The Notch pathway has gained growing attention in chronic lymphocytic leukemia (CLL) because of the high rate of somatic mutations of the NOTCH1 gene." (PMID 35740661, 2022). "Several other types of leukemia also arise from PEST domain mutations in NOTCH1, including chronic lymphocytic leukemia (CLL), and Diffuse Large B cell lymphoma." (PMID 36406268, 2022). "NOTCH1 mutations and deregulated signal have been commonly found in chronic lymphocytic leukemia (CLL) patients." (PMID 34123837, 2021). "It has been reported that the NOTCH1 mutations are associated with reduced benefit of anti-CD20 chemoimmunotherapy regimens in chronic lymphocytic leukemia, and its clinical significance in DLBCL is unclear." (PMID 34956871, 2021). "There is significant association between NOTCH1 mutations and relapse, disease progression, and mortality when compared to B cell CLL patients with wild type." (PMID 32458636, 2020). "NOTCH1 mutations were significantly associated with higher BM lymphocytes in B cell CLL patients (P=0.001)." (PMID 32458636, 2020). "NOTCH1 mutated B cell CLL patients showed more disease progression as compared with wild type CLL patients." (PMID 32458636, 2020). "The aim of this study was to detect the prevalence of NOTCH1 mutations among a cohort of Egyptian patients with B cell CLL, as well as, it’s relation to disease behavior and patient outcome." (PMID 32458636, 2020). "NOTCH1 mutated B cell CLL cases showed statistically significant shorter OS when compared to those with no mutations (P= 0.049)." (PMID 32458636, 2020). "On the other hand, NOTCH1 mutations were significantly associated with shorter mean LDT as compared to B cell CLL patients with wild type (P = 0.049)." (PMID 32458636, 2020). "NOTCH1 mutations were detected in 45.7% of B cell CLL cases; and this figure is higher than was previously reported 24%." (PMID 32458636, 2020). "NOTCH1 mutated B cell CLL cases showed shorter overall survival (OS) as compared with NOTCH1 wild type patients." (PMID 32458636, 2020). "Activating mutations in NOTCH1 have also been identified in chronic lymphocytic leukemia, non-small cell lung carcinoma, and translocations involving NOTCH1/2 in patients with triple negative breast cancer." (PMID 30967879, 2018). "Frequency of genetic variants of NOTCH1 mutations across different chronic lymphocytic leukemia studies." (PMID 29998084, 2018). "In diagnostic and clinical trial cohorts, patients suffered from chronic lymphocytic leukemia with Notch1 coding mutations or noncoding mutations exhibited reduced survival." (PMID 28030818, 2017). "NOTCH1 is recurrently affected by activating mutations in about 10-20% of chronic lymphocytic leukemias and mantle cell lymphomas, and in a lower fraction of diffuse large B cell lymphomas, follicular lymphomas and splenic marginal zone lymphomas." (PMID 27566587, 2016).